DHX9 (DExH-box helicase 9)
Description:
Multifunctional ATP-dependent nucleic acid helicase that unwinds DNA and RNA in a 3' to 5' direction and that plays important roles in many processes, such as DNA replication, transcriptional activation, post-transcriptional RNA regulation, mRNA translation and RNA-mediated gene silencing. Requires a 3'-single-stranded tail as entry site for acid nuclei unwinding activities as well as the binding and hydrolyzing of any of the four ribo- or deoxyribo-nucleotide triphosphates (NTPs). Unwinds numerous nucleic acid substrates such as double-stranded (ds) DNA and RNA, DNA:RNA hybrids, DNA and RNA forks composed of either partially complementary DNA duplexes or DNA:RNA hybrids, respectively, and also DNA and RNA displacement loops (D- and R-loops), triplex-helical DNA (H-DNA) structure and DNA and RNA-based G-quadruplexes. Binds dsDNA, single-stranded DNA (ssDNA), dsRNA, ssRNA and poly(A)-containing RNA. Also binds to circular dsDNA or dsRNA of either linear and/or circular forms and stimulates the relaxation of supercoiled DNAs catalyzed by topoisomerase TOP2A. Plays a role in DNA replication at origins of replication and cell cycle progression. Plays a role as a transcriptional coactivator acting as a bridging factor between polymerase II holoenzyme and transcription factors or cofactors, such as BRCA1, CREBBP, RELA and SMN1. Binds to the CDKN2A promoter. Plays several roles in post-transcriptional regulation of gene expression. In cooperation with NUP98, promotes pre-mRNA alternative splicing activities of a subset of genes. As component of a large PER complex, is involved in the negative regulation of 3' transcriptional termination of circadian target genes such as PER1 and NR1D1 and the control of the circadian rhythms (By similarity). Also acts as a nuclear resolvase that is able to bind and neutralize harmful massive secondary double-stranded RNA structures formed by inverted-repeat Alu retrotransposon elements that are inserted and transcribed as parts of genes during the process of gene transposition. Involved in the positive regulation of nuclear export of constitutive transport element (CTE)-containing unspliced mRNA. Component of the coding region determinant (CRD)-mediated complex that promotes cytoplasmic MYC mRNA stability. Plays a role in mRNA translation. Positively regulates translation of selected mRNAs through its binding to post-transcriptional control element (PCE) in the 5'-untranslated region (UTR). Involved with LARP6 in the translation stimulation of type I collagen mRNAs for CO1A1 and CO1A2 through binding of a specific stem-loop structure in their 5'-UTRs. Stimulates LIN28A-dependent mRNA translation probably by facilitating ribonucleoprotein remodeling during the process of translation. Plays also a role as a small interfering (siRNA)-loading factor involved in the RNA-induced silencing complex (RISC) loading complex (RLC) assembly, and hence functions in the RISC-mediated gene silencing process. Binds preferentially to short double-stranded RNA, such as those produced during rotavirus intestinal infection. This interaction may mediate NLRP9 inflammasome activation and trigger inflammatory response, including IL18 release and pyroptosis. Finally, mediates the attachment of heterogeneous nuclear ribonucleoproteins (hnRNPs) to actin filaments in the nucleus. (Microbial infection) Plays a role in HIV-1 replication and virion infectivity. Enhances HIV-1 transcription by facilitating the binding of RNA polymerase II holoenzyme to the proviral DNA. Binds (via DRBM domain 2) to the HIV-1 TAR RNA and stimulates HIV-1 transcription of transactivation response element (TAR)-containing mRNAs. Involved also in HIV-1 mRNA splicing and transport. Positively regulates HIV-1 gag mRNA translation, through its binding to post-transcriptional control element (PCE) in the 5'-untranslated region (UTR). Binds (via DRBM domains) to a HIV-1 double-stranded RNA region of the primer binding site (PBS)-segment of the 5'-UTR, and hence stimulates DHX9 incorporation into virions and virion infectivity. Also plays a role as a cytosolic viral MyD88-dependent DNA and RNA sensors in plasmacytoid dendritic cells (pDCs), and hence induce antiviral innate immune responses. Binds (via the OB-fold region) to viral single-stranded DNA unmethylated C-phosphate-G (CpG) oligonucleotide.
Synonyms: LKP; DDX9; NDH2; RHA; MRD75; NDHII
Tractability: Small molecule: a structure with a bound ligand is known; it has a binding pocket of medium quality. PROTAC: UniProt records ubiquitination sites on it; ubiquitination databases record sites on it; its protein half-life has been measured.
Target class: Enzyme; Hydrolase
Gene: Protein-coding gene on chromosome 1 (182,839,302 to 182,887,982, forward strand). Ensembl gene ENSG00000135829.
Subcellular location: Nucleus; Nucleus, nucleoplasm; Nucleus, nucleolus; Cytoplasm; Cytoplasm, cytoskeleton, microtubule organizing center, centrosome
Subcellular location (Human Protein Atlas): Nucleoplasm; Nucleoli
Pathways (Reactome):
Immune System: DEx/H-box helicases activate type I IFN and inflammatory cytokines production; PKR-mediated signaling; RIP-mediated NFkB activation via ZBP1
Metabolism of RNA: mRNA Polyadenylation; mRNA Splicing - Major Pathway
Disease: Dengue Virus-Host Interactions
Gene Ontology:
Molecular function: 3'-5' DNA helicase activity; 3'-5' DNA/RNA helicase activity; 3'-5' RNA helicase activity; ATP binding; ATP hydrolysis activity; chromatin DNA binding; DNA helicase activity; DNA replication origin binding; double-stranded DNA binding; double-stranded RNA binding; G-quadruplex unwinding activity; importin-alpha family protein binding; mRNA binding; nucleoside triphosphate diphosphatase activity; promoter-specific chromatin binding; protein binding; regulatory region RNA binding; ribosome binding; RISC complex binding; RNA binding; RNA helicase activity; RNA polymerase binding; RNA polymerase II cis-regulatory region sequence-specific DNA binding; RNA polymerase II complex binding; RNA polymerase II-specific DNA-binding transcription factor binding; and 12 more
Biological process: alternative mRNA splicing, via spliceosome; cellular response to exogenous dsRNA; chromatin organization; CRD-mediated mRNA stabilization; DNA-templated viral transcription; miRNA-mediated post-transcriptional gene silencing; negative regulation of nuclear-transcribed mRNA catabolic process, deadenylation-dependent decay; osteoblast differentiation; positive regulation of cytoplasmic translation; positive regulation of DNA repair; positive regulation of DNA replication; positive regulation of fibroblast proliferation; positive regulation of interferon-alpha production; positive regulation of interferon-beta production; positive regulation of interleukin-6 production; positive regulation of response to cytokine stimulus; positive regulation of RNA export from nucleus; positive regulation of transcription by RNA polymerase II; positive regulation of tumor necrosis factor production; positive regulation of viral transcription; protein localization to cytoplasmic stress granule; protein-containing complex assembly; regulation of cytoplasmic translation; regulation of mRNA processing; regulation of transcription by RNA polymerase II; and 6 more
Cellular component: actin cytoskeleton; centrosome; CRD-mediated mRNA stability complex; cytoplasm; cytoplasmic ribonucleoprotein granule; cytosol; membrane; nuclear body; nuclear stress granule; nucleolus; nucleoplasm; nucleus; perichromatin fibrils; protein-containing complex; ribonucleoprotein complex; RISC complex; RISC-loading complex
Genetic constraint (gnomAD): Loss-of-function variants: 26 observed, 137.04 expected, observed/expected ratio (o/e) 0.19, 90% interval 0.14 to 0.26. The upper end of that interval is the gene's LOEUF score, 0.26, which puts it in group 1 of 6, group 1 being the genes least tolerant of losing a copy. Missense variants: 756 observed, 1,530.4 expected, observed/expected ratio (o/e) 0.49, 90% interval 0.46 to 0.52. Synonymous variants: 505 observed, 512.99 expected, observed/expected ratio (o/e) 0.98, 90% interval 0.91 to 1.06.
Homologues: Orthologues: chimpanzee DHX9 (100% identical), macaque DHX9 (99% identical), dog DHX9 (95% identical), pig DHX9 (94% identical), rabbit DHX9 (94% identical), mouse Dhx9 (92% identical), rat Dhx9 (92% identical), guinea pig DHX9 (91% identical), tropical clawed frog dhx9 (79% identical), zebrafish dhx9 (77% identical), Drosophila melanogaster mle (51% identical), Caenorhabditis elegans rha-1 (43% identical). Paralogues in human: DHX57 (28% identical), YTHDC2 (27% identical), DHX29 (26% identical), DHX36 (25% identical), DHX30 (24% identical), TDRD9 (20% identical), DHX34 (19% identical), DHX8 (19% identical), DHX16 (18% identical), DHX38 (17% identical), DHX37 (17% identical), DHX15 (16% identical), and 6 more.
Diseases named in the same sentence as DHX9 in open-access papers:
DHX9 is named in the same sentence as 117 diseases in open-access papers, as found by Europe PMC text mining. Sharing a sentence is not in itself a finding about the gene and the disease. The quoted sentences say what the papers report.
Ewing sarcoma (33 papers, 2012 to 2025). A small round cell tumor that lacks morphologic, immunohistochemical, and electron microscopic evidence of neuroectodermal differentiation. "For example, the RNA DExH-box helicase 9 (DHX9) is associated with Ewing sarcoma, an aggressive cancer of the bone and soft tissue that typically affects younger adults." (PMID 34899861, 2021). "We also found that the expression of hnRNPM and SRSF3, which showed the strongest repression of exon 6A inclusion, is highly associated with the expression of DHX9 in Ewing sarcoma patients." (PMID 32023846, 2020). "Herein, by querying Ewing sarcoma datasets of patients, we found that the expression of DHX9 is positively associated with disease progression and worse prognosis." (PMID 32023846, 2020). "A small molecule inhibitor targeting the interaction between the oncogenic fusion protein EWS-FLI1 and its transcriptional partner DHX9 was developed for Ewing sarcoma treatment." (PMID 40427154, 2025). "Downregulation of SRSF3 or hnRNPM can inhibit the expression of DHX9 and the proliferation of Ewing’s sarcoma cells, and enhance the sensitivity of Ewing’s sarcoma cells to chemotherapy." (PMID 36338707, 2022). "Inhibition of the EWS-FLI1/DHX9 interaction by small molecules (YK-4-279 and TK-216) was shown to repress Ewing sarcoma growth." (PMID 35590370, 2022). "In Ewing sarcoma, DHX9 promotes EWS-FLI1 transcriptional activity and contributes to oncogenic transformation." (PMID 35326688, 2022). "The small molecule YK-4-279 was originally identified by surface plasmon resonance (SPR) and developed for Ewing’s sarcoma to block EWS-FLI1 binding to DHX9/RNA helicase A (RHA), an important cofactor for its oncogenic activity." (PMID 35267426, 2022). "DHX9 depletion or inhibition of EWS-FLI1/DHX9 interaction inhibited Ewing sarcoma cell growth and improved sensitivity to therapies." (PMID 35590370, 2022). "For instance, DHX9 cooperates with the oncogenic transcription factor EWS-FLI1 in Ewing sarcoma to promote oncogenic transformation." (PMID 35590370, 2022). "An RNA-based therapeutic triggering poison exon inclusion in DHX9, a gene involved in Ewing sarcoma, has been exploited to enhance the efficacy of chemotherapy in cancer patients." (PMID 33411788, 2021). "Higher DHX9 expression levels are correlated with worse prognosis for Ewing sarcoma patients, making DXH9 a potential cancer therapeutic target." (PMID 34899861, 2021). "SRSF3 depletion displayed a stronger effect than HNRNPM depletion on Ewing sarcoma sensitivity to chemotherapy treatment, in line with its stronger impact on DHX9 expression." (PMID 32023846, 2020). "As previously reported, disruption of the DHX9-EWS-FLI1 interaction strongly impacts on the EWS-FLI1-driven transcriptional program in Ewing sarcoma cells." (PMID 32023846, 2020). "As previously discussed, DHX9 binds EWS-FLI1 in Ewing sarcoma, enhancing EWS-FLI1-dependent transcription." (PMID 33437516, 2020). "Collectively these results unveil a novel role for SRSF3 and hnRNPM in the regulation of DHX9 alternative splicing, which also impacts on Ewing sarcoma cell sensitivity to chemotherapeutic treatments." (PMID 32023846, 2020). "Both UV light irradiation and etoposide treatment induced this event by slowing down the RNAPII, with the consequent decrease in DHX9 expression, thus leading to higher sensitivity of Ewing sarcoma cells to genotoxic stress." (PMID 32023846, 2020). "In this study, by employing multiple approaches, we have now identified several splicing factors (SRSF1, SRSF3, and SRSF10, hnRNPK, hnRNPM, and FUS) as regulators of DHX9 splicing in Ewing sarcoma cells." (PMID 32023846, 2020). "In Ewing sarcoma, DHX9 forms a complex with the EWS-FLI1 oncoprotein and modulates EWS-FLI1-dependent transcription." (PMID 32023846, 2020).
Ewing sarcoma (continued). "This work highlights DHX9’s ability to form alternative complexes with either EWS-FLI1 or pncCCND1_B/Sam68 in modulating CCND1 expression in Ewing sarcoma cells, exhibiting both oncogenic and tumor suppressive functions." (PMID 33437516, 2020). "Remarkably, silencing of SRSF3 and HNRNPM, impacts on DHX9 expression as well as on Ewing sarcoma cell viability and proliferation, while it reduces survival of Ewing sarcoma cells to doxorubicin treatment." (PMID 32023846, 2020). "In conclusion, our study shows that DHX9 expression in Ewing sarcoma correlates with worse outcome in patients." (PMID 32023846, 2020). "Inclusion of poison-exon 6A in DHX9 would usually target it to nonsense-mediated mRNA decay, however, in Ewing sarcoma DHX9 expression is upregulated following repression of this exon and correlates with a poor prognosis." (PMID 33437516, 2020). "In Ewing sarcoma cells, two mutually exclusive complexes occur, formed by DHX9 with either EWS-FLI1 or Sam68/pncCCND1_B." (PMID 32722129, 2020). "DHX9 is a key player in Ewing sarcoma malignancy, and its expression correlates with worse prognosis in patients." (PMID 32023846, 2020). "Downregulation of these proteins inhibits DHX9 expression, suppresses proliferation and sensitizes Ewing sarcoma cells to doxorubicin treatment, revealing the importance of DHX9 alternative splicing in conferring chemosensitivity or chemoresistance." (PMID 33437516, 2020). "We identified hnRNPM and SRSF3 as key factors required to suppress exon 6A inclusion and maintain high DHX9 expression in Ewing sarcoma cells." (PMID 32023846, 2020). "Although originally reported as an agent that selectively disrupts the EWS-FLI/DHX9 interaction in Ewing's sarcoma, our study suggests that YK-4-279 is capable of targeting a much wider variety of cancers." (PMID 28602975, 2017). "Indeed, R-loop accumulation is a common feature of cancer cells, and multiple members of the DEAD/H helicase family including DHX9 are strongly enriched and frequently deregulated in a wide range of cancers including Ewing sarcoma." (PMID 35326688, 2022). "Importantly, knockdown of HNRNPM or SRSF3 lowered DHX9 protein levels, decreased the viability and proliferation of an Ewing sarcoma cell line, and rendered the cells more sensitive to chemotherapeutics." (PMID 34899861, 2021). "Furthermore, downregulation of SRSF3 or hnRNPM inhibited DHX9 expression and Ewing sarcoma cell proliferation, while sensitizing cells to chemotherapeutic treatment." (PMID 32023846, 2020). "Nevertheless, the mechanism that suppresses the inclusion of this poison exon and supports high DHX9 expression in Ewing sarcoma cells was unknown." (PMID 32023846, 2020). "DHX9 also interacts with the RBP Sam68 and with the promoter-associated noncoding RNA pncCCND1b to form an RNA-protein complex inhibiting CCND1 transcription in Ewing sarcoma cells." (PMID 32023846, 2020). "Analysis of event-free survival and overall survival in a dataset comprising 64 Ewing sarcoma, 4 Askin, and 20 perypheral primitive neuroectodermal tumors, which all belong to the family of Ewing tumors, showed that high DHX9 expression correlates with worse prognosis of the patients." (PMID 32023846, 2020). "The EWS-FLI1/DHX9 complex represents a good therapeutic target for Ewing sarcoma." (PMID 32023846, 2020). "Notably, the effect of SRSF3 knockdown on DHX9 protein expression and Ewing sarcoma cell viability was stronger than that elicited by hnRNPM, although displaying a milder effect on the inclusion of the alternative poison exon." (PMID 32023846, 2020). "Given the functional relevance of DHX9 in genomic instability and in cancer, we asked whether its expression represents a prognostic factor in Ewing sarcoma." (PMID 32023846, 2020).
Ewing sarcoma (continued). "Moreover, our work indicates that the silencing of hnRNPM and SRSF3, the strongest repressors of exon 6A, significantly reduces DHX9 expression and Ewing sarcoma cell survival, thus suggesting the functional relevance of their effects on DHX9 splicing regulation." (PMID 32023846, 2020). "To test whether the expression of splicing factors involved in exon 6A regulation was correlated with DHX9 mRNA levels in Ewing sarcoma patients, we performed Pearson correlation analyses using a dataset of 64 Ewing sarcoma patients, 4 Askin, and 20 PNET tumors." (PMID 32023846, 2020). "Additionally, DHX9 expression can be tuned to improve chemosensitivity of Ewing sarcoma cells." (PMID 33437516, 2020). "Thus, YK-4-279 treatment, as well as DHX9 downregulation, could represent a targetable opportunity for Ewing sarcoma, and the TK-216 derivative has recently concluded phase I/II trial as a monotherapy and in combination with vincristine in relapsed or refractory Ewing sarcoma patients." (PMID 40427154, 2025). "In contrast, the interactions between DHX9 and YBX1, proteins with known roles in Ewing sarcoma, were greatly attenuated in the presence of high salt and RNase A." (PMID 36793594, 2023). "Similar results were also obtained in SK-N-MC and LAP-35 Ewing sarcoma cells, even though HNRNPM and SRSF3 knockdown in LAP-35 weakly affected DHX9 alternative splicing." (PMID 32023846, 2020). "Similar results were obtained in SK-N-MC, whereas LAP-35 Ewing sarcoma cells displayed only a slight decrease in the EC50, in line with the more modest effect on DHX9 exon 6A inclusion." (PMID 32023846, 2020). "Notably, DHX9 expression correlates with that of SRSF3 and hnRNPM in Ewing sarcoma patients." (PMID 32023846, 2020). "Since high DHX9 expression correlates with poor prognosis, these results suggest that regulation of DHX9 expression by SRSF3 and hnRNPM could represent a prognostic factor in Ewing sarcoma pathogenesis." (PMID 32023846, 2020). "Thus, the regulation of cyclin D1 expression in Ewing sarcoma cells results from the mutually exclusive binding of two different complexes to the CCND1 promoter: one composed by EWS-FLI1 and DHX9, promoting cyclin D1 expression, and a repressive complex formed by Sam68, DHX9, and pncCCND1_B." (PMID 32722129, 2020). "Noteworthy, although we focused on the DHX9 poison-exon as a splicing target of SRSF3 and hnRNPM with direct relevance for Ewing sarcoma, our findings do not rule out possible effects of these RBPs on other splicing variants of the same or other genes in this disease." (PMID 32023846, 2020).